CD47 (CD47 molecule)
Diseases named in the same sentence as CD47 in open-access papers (continued):
Sharing a sentence is not in itself a finding about the gene and the disease.
malignant meningioma (2 papers, 2023 to 2024). "Recent studies have indicated that CD47 expression in malignant meningiomas was increased while the number of T cells was decreased, and the number of macrophages expressing CD68 was increased." (PMID 38404571, 2024). "We found that the expression of CD47 was increased in malignant meningioma along with a decreased number of T cells and an increase in CD68+ macrophages." (PMID 37171006, 2023). "To sum up, we should realize that CD47 blockade plays a practical and effective role in eliminating tumor immune escape and inhibiting the proliferation and migration of malignant meningioma." (PMID 37171006, 2023). "Our results demonstrated that CD47 maybe involved in the meningioma progression and prognosis and offered a novel therapeutic option by targeting CD47 in malignant meningioma." (PMID 37171006, 2023). "It is believed that with the development of targeting technology and drug targeting carriers, anti-CD47 drugs will be targeted and quantitatively acted on local tumor tissues, especially tumors such as malignant meningioma, so as to achieve the effective cure of tumors." (PMID 37171006, 2023). "We have verified previously that CD47 was highly expressed in malignant meningioma." (PMID 37171006, 2023). "Finally, p-ERK and EGFR showed higher expression in malignant meningioma with high expression of CD47, which was verified by western blot." (PMID 37171006, 2023). "Meanwhile, we found that CD68+ macrophages showed an increased expression in malignant meningioma, which indicated blocking CD47 maybe a potential therapeutic target for malignant meningioma." (PMID 37171006, 2023). "Finally, Kaplan-Meier survival analysis also showed that the overall survival in CD47-low group was better than that in CD47-high group of malignant meningioma (P = 0.035)." (PMID 37171006, 2023). "However, the results of immunohistochemistry suggested that compared with PD-L1, the expression of CD47 was higher in malignant meningioma which indicated CD47 blockade maybe more effective in treating malignant meningioma." (PMID 37171006, 2023). "Moreover, we conducted in vitro and in vivo experiments to find whether anti-CD47 antibody could suppress the proliferation of malignant meningioma and promote the macrophage-mediated phagocytosis." (PMID 37171006, 2023). "Furthermore, in vitro experiments indicated that CD47 could enhance the cell growth, migration and invasion of IOMM-Lee cells and CD47 blockade could promote the phagocytosis of malignant meningioma cells by macrophages." (PMID 37171006, 2023). "However, the role of CD47 in malignant meningioma is not well understood." (PMID 37171006, 2023). "The human malignant meningioma cell line IOMM-Lee cells were firstly treated with or without anti-CD47 antibody (B6H12) or IgG1 isotype control." (PMID 37171006, 2023). "So we conducted the experiments above and found that anti-CD47 antibody (B6H12) could indeed inhibit the proliferation, migration and invasion ability of malignant meningioma." (PMID 37171006, 2023). "However, the role of CD47 in tumor immunity has not been studied in malignant meningioma." (PMID 37171006, 2023). "However, no one has reported the effect of anti-CD47 on malignant meningioma." (PMID 37171006, 2023).
meningioma (2 papers, 2023 to 2024). A generally slow growing tumor attached to the dura mater. "However, CD47 associated signaling pathways in malignant meningioma are still limited." (PMID 37171006, 2023). "Blocking CD47 with an anti-CD47 antibody inhibited the growth and movement of malignant meningioma cells and promoted phagocytosis mediated by macrophages." (PMID 38404571, 2024). "Although the expression levels of PD-L1 and CD47 increased with the malignant degree of meningioma, the expression level of CD47 was higher than that of PD-L1 in all grades of meningioma." (PMID 37171006, 2023). "Along with that, the expression of p-ERK and EGFR was also remarkablely down-regulated in si-CD47 group cells, indicating the MAPK and EGFR signaling pathways were regulated by CD47 in malignant meningioma cells." (PMID 37171006, 2023). "The results indicated that the expression of CD47 in malignant meningioma cells was significantly inhibited in si-CD47 group compared with si-NC and NC groups." (PMID 37171006, 2023). "Meanwhile, Dual immunofluorescence staining of malignant meningioma showed that CD47 was mainly expressed on the membrane of EMA-positive tumor cells." (PMID 37171006, 2023). "We collected 190 clinical meningioma samples and detected the expression of CD47 and immune infiltration in WHO grade I-III by immunohistochemistry, western blot, qPCR." (PMID 37171006, 2023). "To test the possibility of immunotherapy in meningioma treatment, we first detected the expression levels of immune checkpoints CD47 and PD-L1 in meningioma samples by using immunohistochemistry." (PMID 37171006, 2023). "In light of these previous findings, we collected 190 meningioma samples to assess the expression of CD47 and the infiltration of immune cells." (PMID 37171006, 2023). "Surprisingly, our results showed that the expression of CD47 was higher in WHO grade III meningioma than that of grade I and II." (PMID 37171006, 2023). "Our results showed that CD47 was highly expressed in meningioma and was closely related to the prognosis of meningioma, and macrophages were the major types of the immune cells in meningioma compared with other immune cells." (PMID 37171006, 2023). "Collectively, these results suggested that CD47 was highly expressed in meningioma and was closely related to the prognosis of meningioma, which maybe serve as a potential therapeutic target of meningioma." (PMID 37171006, 2023). "Results revealed that SIRPα was co-expressed with CD68 both in malignant meningioma tissues and mouse subcutaneous xenografts, indicating that the phagocytosis of malignant meningioma cells by macrophages maybe mediate by CD47-SIRPα axis." (PMID 37171006, 2023). "In sum, our results indicated that CD47 maybe serve as a potential therapeutic target of meningioma." (PMID 37171006, 2023). "Moreover, we examined the expression of signal regulatory protein-alpha (SIRPα), one of the most important receptor of CD47, in both malignant meningioma tissues and mouse subcutaneous xenografts derived from the human malignant meningioma cell line IOMM-Lee." (PMID 37171006, 2023). "Therefore, CD47 may mediate the immune escape of malignant meningioma cells via CD47-SIRPα interaction." (PMID 37171006, 2023). "Furthermore, the expression of EGFR was higher in CD47 high expression group, which suggesting CD47 may affect the progression of meningioma by affecting EGFR pathway." (PMID 37171006, 2023). "Therefore, we tested whether CD47 influenced the proliferation, migration and invasion of malignant meningioma cells in vitro." (PMID 37171006, 2023). "Additionally, the anti-tumor effect of MIAP301 was found to be partly blocked under the condition of macrophage depletion, as anti-CD47 itself could not only promote the phagocytosis of macrophages to meningioma, but also inhibit the proliferation and migration of meningioma." (PMID 37171006, 2023).
meningioma (continued). "Thus, To verify that CD47 blockade would promote the phagocytosis of malignant meningioma cells by macrophages, malignant meningioma cells and macrophages were co-cultured with or without the presence of anti-CD47 antibody (B6H12) or IgG1 isotype control." (PMID 37171006, 2023). "Furthermore, we tested the effect of anti-CD47 by using two different clones of anti-CD47 antibody (B6H12 and MIAP301) in vivo and the results showed that both B6H12 and MIAP301 could inhibit the progression of meningioma, which was consistent with the findings of previous study on other tumors." (PMID 37171006, 2023).
metabolic dysfunction-associated steatotic liver disease (2 papers, 2021 to 2025). Metabolic dysfunction-associated steatotic liver disease (MASLD, formerly known as nonalcoholic fatty liver disease or NAFLD) is a type of liver disease that is not caused by alcohol. "Although significant progress has been made in understanding the role of CD47 in metabolic dysfunction-associated steatotic liver disease (MASLD), key questions remain." (PMID 40630093, 2025).
mucoepidermoid carcinoma (2 papers, 2022 to 2025). A carcinoma morphologically characterized the presence of cuboidal mucous cells, goblet-like mucous cells, squamoid cells, cystic changes, and a fibrotic stromal formation. "Analysis across major SGC subtypes—including salivary duct, adenoid cystic, and mucoepidermoid carcinomas—reveals that CD47 expression is prominent not only on malignant cells but also on tumor-infiltrating immune cells (TIICs)." (PMID 41164198, 2025). "In mucoepidermoid carcinoma, for instance, CD47 expression on TIICs was found to be significantly higher than on tumor cells." (PMID 41164198, 2025). "We observed that the CD47+ tumor cells are outnumbered by CD47+ TIICs in mucoepidermoid carcinoma." (PMID 36171566, 2022).
myeloproliferative disorder (2 papers, 2018 to 2021). A clonal hematopoietic stem cell disorder, characterized by proliferation in the bone marrow of one or more of the myeloid (i.e., granulocytic, erythroid, megakaryocytic, and mast cell) lineages. "One previous study demonstrated that CD47 is upregulated in AML and blastic phase CML, but not in other myeloproliferative disorders, including PV, post-PV MF, ET, and PMF (n=5)." (PMID 30539968, 2018).
oral cancer (2 papers, 2019 to 2022). "In total, 14 genes were commonly identified as DEGs in OECM-1 and OC-2 oral cancer cells with CD47-overexpression." (PMID 35678681, 2022). "In addition, we used IPA to analyze the DEGs regulated by CD47-overexpression in oral cancer for network analysis including molecular functions (MFs), biological processes (BPs), and cellular components (CCs)." (PMID 35678681, 2022). "Previous studies showed that CD47-overexpression may regulate the growth process of oral cancer." (PMID 35678681, 2022).
Oral leukoplakia (2 papers, 2016 to 2024). A thickened white patch on the oral mucosa that cannot be rubbed off. "Our previous study showed that CD47 was up-regulated in oral leukoplakia (OLK) and OSCC, suggesting cancer cells may evade phagocytosis of macrophages through the interaction of CD47 with SIRPα." (PMID 27793032, 2016).
osteoporosis (2 papers, 2023 to 2025). A condition of reduced bone mass, with decreased cortical thickness and a decrease in the number and size of the trabeculae of cancellous bone (but normal chemical composition), resulting in increased fracture incidence. "Taken together, these findings demonstrate that CD47 antibody can mitigate ageing‐related and osteoporosis‐associated bone loss by promoting osteoblast activity, reducing adipocyte accumulation, and suppressing osteoclast activity." (PMID 40514348, 2025). "Taken together, the CD47 antibody effectively delays ageing processes in aged mice and inhibits osteoporosis progression in OVX mice, highlighting a potential approach for targeting age‐related bone diseases." (PMID 40514348, 2025). "THBS3 could down‐regulate the expression of its downstream target CD47 and delay the process of bone loss in aged mice and OVX mice, which may provide a novel frontier for the treatment of osteoporosis." (PMID 40514348, 2025).
parasitemia (2 papers, 2016 to 2020). "Beside bacterial and parasitic infections, lack of CD47 enhances virus specific neutralizing antibodies response during influenza virus infection." (PMID 32882841, 2020).
peritonitis (2 papers, 2010 to 2015). Inflammation of the peritoneum (tissue that lines the abdominal wall and covers most of the organs in the abdomen). "PMN recruitment in cd47-/- mice was not impaired in zymosan-induced peritonitis, suggesting that recruitment in response to fungal pathogen-associated molecular patterns (PAMPs) does not depend on CD47." (PMID 26010544, 2015).
rectal cancer (2 papers, 2023 to 2025). A primary or metastatic malignant neoplasm that affects the rectum. "The up-regulation of PD-L1 and CD47 in rectal cancer cells, however, may block this effect." (PMID 37232754, 2023).
renal carcinoma (2 papers, 2023 to 2025). A carcinoma arising from the epithelium of the renal parenchyma or the renal pelvis. "IMM40H exhibited a synergistic effect with CD47-targeted IMM01 in treating A498 xenograft renal carcinoma model." (PMID 37849799, 2023). "CD47, a bridge between innate and adaptive immunity, acts as the downstream effector molecule of the SMYD3 signal to promote the infiltration of T helper 2 (Th2) cells, protecting renal cancer cells from immune attack." (PMID 40548645, 2025).
scleroderma (2 papers, 2020 to 2023). Scleroderma is a rare autoimmune connective tissue disorder characterized by abnormal hardening of the skin and, sometimes, other organs. "In summary, we were able to demonstrate that blocking CD47 and IL-6 prevented the loss in fat tissue during disease initiation, reversed fibrotic skin changes thereafter, and eliminated human scleroderma fibroblasts in an adaptive transfer model." (PMID 32814713, 2020). "However, the loss of fat tissue with stiffening of the skin is a hallmark of scleroderma, and CD47/IL-6 increased the dermal fat content." (PMID 32814713, 2020). "Therapeutically, combined CD47 and IL-6 blockade reversed skin fibrosis in mice and led to the rapid elimination of ectopically transplanted scleroderma cells." (PMID 32814713, 2020). "Because our results had shown that both hedgehog signaling and IL-6 contributed to scleroderma, we combined both immune therapies either with vismodegib (CD47/PD-L1 inhibition + vismodegib) or with the IL-6 inhibitor tocilizumab (CD47/IL-6 inhibition)." (PMID 32814713, 2020). "In accordance with these findings, CD47/IL-6 blockade accelerated the elimination of human scleroderma fibroblasts and increased apoptosis in an adaptive transfer model." (PMID 32814713, 2020). "In this study, we evaluated the efficiency of the “don’t-eat-me-signal” CD47 either alone or in combination with an IL-6 inhibitor in a scleroderma mouse model." (PMID 32814713, 2020). "Altogether, our study demonstrates the efficiency of combining different immunotherapies in treating scleroderma and provides a rationale for combining CD47 and IL-6 inhibition in clinical trials." (PMID 32814713, 2020). "At the beginning, we determined if JUN, CD47, and PD-L1 are commonly upregulated in human scleroderma." (PMID 32814713, 2020). "By extension, our results showing depletion of scleroderma fibroblasts from skin xenografts may be due to insufficient activation of mouse macrophage Sirpa by human CD47 on scleroderma fibroblasts." (PMID 37669366, 2023). "Finally, we evaluated if CD47/IL-6 inhibition accelerates the elimination of transplanted human scleroderma fibroblasts in an adaptive transfer model." (PMID 32814713, 2020). "Considering that scleroderma leads to the accumulation of diseased fibroblasts, we hypothesized that the inhibition of the “don’t-eat-me-signal” CD47 would help the body’s immune system remove abnormal fibroblasts." (PMID 32814713, 2020). "In the second part of this study, we aimed at characterizing our mouse model to better interpret our results from the treatment with the CD47 inhibitor because we had to identify whether our Jun-driven mouse model overlaps with human scleroderma." (PMID 32814713, 2020). "Here, we evaluated whether scleroderma fibroblasts take advantage of the “don’t-eat-me-signal” CD47 and whether blocking CD47 enables the body’s immune system to get rid of diseased fibroblasts." (PMID 32814713, 2020). "Importantly, the promoters of CD47 and PD-L1 were more easily accessible in scleroderma, suggesting that the abnormal fibroblasts use “don’t-eat-me-signals” and immune checkpoints as a protective mechanism against the host’s immune system." (PMID 32814713, 2020). "CD47/IL-6 inhibition eliminates scleroderma fibroblasts in an adaptive transfer model." (PMID 32814713, 2020). "Combined CD47 and IL6 inhibition eliminates diseased fibroblasts and reverses skin fibrosis in a murine scleroderma model." (PMID 32814713, 2020). "We first demonstrated in patient samples that scleroderma upregulated transcription factor JUN and increased promoter accessibilities of both JUN and CD47." (PMID 32814713, 2020). "Regarding the good safety profiles of currently available CD47- and IL-6–blocking agents, we believe that our study gives enough evidence to safely try combined immunotherapy with CD47 and IL-6 inhibition in patients with highly fibrotic and stable, nonprogressive scleroderma." (PMID 32814713, 2020).
serous adenocarcinoma (2 papers, 2017 to 2022). An adenocarcinoma that is characterized by the presence of papillary patterns and cellular budding. "To exclude the impact of pathology grade and clinical FIGO stages on CD47 expression in patient survival, we assessed 29 FIGO stage III-IV patients with poorly differentiated serous adenocarcinoma for 50 months." (PMID 28380460, 2017).
Sézary syndrome (2 papers, 2021 to 2022). "Similarly to alemtuzumab, most patients with Sézary syndrome may benefit from a combination of lacutamab with anti-CD47 agents." (PMID 36429020, 2022). "These are the same side effects encountered with CD47 blockers, so presumably, a combination of the two would not resolve them; currently, a trial of mogamulizumab in combination with magrolimab is in the recruitment phase for patients with R/R stage IB-IV MF or Sézary syndrome (NCT04541017)." (PMID 36429020, 2022).
Type 1 Diabetes (2 papers, 2021 to 2025). "We also show that TSP1 is likely the soluble ligand involved in CD47 activation, with clear upregulation in islets under these conditions, as well as in the human pancreas affected by type 1 diabetes." (PMID 40133488, 2025). "Both CD47 and TSP1 expression were increased in pancreases of humans with type 1 diabetes, as were plasma levels of TSP1." (PMID 40133488, 2025). "We previously demonstrated upregulation of CD47 expression in endocrine pancreas of NOD mice and now showed that both CD47 and TSP1 were upregulated in human pancreas from donors with type 1 diabetes compared with healthy non-diabetic donors." (PMID 40133488, 2025).
uterine corpus endometrial carcinoma (2 papers, 2021 to 2025). A endometrial carcinoma (disease) that involves the body of uterus. "The survival analysis in uterine corpus endometrial carcinoma demonstrates a higher survival probability of individuals with medium/low expression levels of CD47, than individuals with high expression levels of this gene." (PMID 34439361, 2021).
Wiskott-Aldrich syndrome (2 papers, 2013 to 2020). Wiskott-Aldrich syndrome (WAS) is a primary immunodeficiency disease characterized by microthrombocytopenia, eczema, infections and an increased risk for autoimmune manifestations and malignancies. "Furthermore, CD47 ligation did not result in cell death of mononuclear cells from patients with Wiskott-Aldrich syndrome, implicating a requirement for Cdc42 – an upstream GTPase for Arp2/3 activation – in CD47-mediated cell death." (PMID 33224442, 2020). "In support of a role for the actin cytoskeleton, peripheral blood mononuclear cells (PBMCs) from Wiskott-Aldrich syndrome (WAS) patients, where mutations in the WAS protein (WASP) results in defective Cdc42-induced regulation of the actin cytoskeleton, are resistant to CD47-induced apoptosis." (PMID 23401787, 2013).